ADA (adenosine deaminase)
Diseases named in the same sentence as ADA in open-access papers (continued):
Sharing a sentence is not in itself a finding about the gene and the disease.
infection (continued). "Of most direct relevance to the possible use of ADA against early infection by SARS-CoV-2 are findings that MERS-CoV entry and infection were prevented with exogenous ADA outcompeting MERS-CoV binding to DPP4." (PMID 33324223, 2020). "To test the effect of AIBP on HIV replication, we first performed titrations to determine the effect of baculovirus-expressed recombinant AIBP on infection of monocyte-derived macrophages (MDMs) by HIV-1 ADA." (PMID 31964734, 2020). "These CD4 +T cells were more susceptible than those of Ctrl to subsequent infection using two different R5-tropic viruses (YU2: Ctrl 1.15 ± 0.05% vs ECr/VCr 2.74 ± 1.11%; p=0.009; ADA: Ctrl 0.70 ± 0.04% vs ECr/VCr 1.79 ± 1.3%; p=0.008)." (PMID 30964004, 2019). "The clinical picture of ADA-deficient SCID is similar to other genetic forms of SCID, with persistent diarrhoea, dermatitis, and serious infections, often caused by opportunistic pathogens such as Pneumocystis jiroveci, being characteristic." (PMID 29690908, 2018). "By day 3 post-infection, 40% of the mock-treated mice had succumbed to the infection, compared to 10% of the ADA-inhibited mice." (PMID 26313746, 2015). "To test its role in resistance against serious infection by S. pneumoniae, we first inhibited adenosine deaminase (ADA), an enzyme responsible for the breakdown of adenosine." (PMID 26313746, 2015). "The results obtained in thisstudy allow for the assessment of important aspects of ADA and contribute to a betterunderstanding of the purinergic system in T. vaginalis and the roleof iron in establishing infection and parasite survival." (PMID 26517498, 2015). "MDM were infected with replication competent HIV-1 (ADA at a multiplicity of infection, MOI, of 0,1)." (PMID 25422070, 2014). "A mutant form of gH in which the RGD motif was substituted to ADA was used in two functional assays: infection and cell-to-cell fusion." (PMID 24367260, 2013). "This study demonstrated the great potential of this technique because it has significant difference in serum ADA levels between children with disease and infection." (PMID 22529869, 2012). "As observed with measurement of infection by p24 production, MDM responded to different TLR ligands in the same way, here by arresting ADA infection prior to viral DNA synthesis." (PMID 21904615, 2011). "Seven days after plating, we exposed MDM to HIV-1 strain ADA at a multiplicity of infection (MOI) of 0.1virus/target cell." (PMID 21637744, 2011). "For infection MDM were treated with supernatants during exposure to ADA and extracellular p24 was measured four days after infection." (PMID 21904615, 2011). "MDM were treated with LPS and infected either with ADA, B.aL, or YU-2 and infection was monitored by p24 expression." (PMID 21904615, 2011). "Adenosine deaminase is a regulator of inflammation, which was down-regulated in liver 22 dpi, while it had a peak in expression at the same stage of infection in the head kidney and spleen." (PMID 18945374, 2008). "The R5 ADA virus replicated rapidly to high levels, attaining peak levels of virus replication at day 7 post-infection." (PMID 19088897, 2007). "The R5X4 89.6 virus also replicated to high levels, but had delayed replication kinetics compared to ADA, reaching peak levels of virus replication at day 14 post-infection." (PMID 19088897, 2007). "Patients previously enrolled in the US Phase 3 study (STP group) and 66.7% of those transitioning from pegademase (PT group) also maintained satisfactory ADA and dAXP levels with stable rates of infections, hospitalizations, and lymphocyte counts for up to 48.6 months." (PMID 40140214, 2025). "In a similar trial, GPM supplementation was able to stop all changes brought on by experimental infection with P. aeruginosa (down-regulation of Nucleoside Triphosphate diphosphohydrolase-NTPDase, with an increase in adenosine deaminase-ADA, metabolites of NOx, MPO and CAT activities)." (PMID 38468965, 2024).
infection (continued). "The mixed-infection group showed higher levels of ADA and Cys-C than the single-infection group." (PMID 36033842, 2022). "A Student's t-test was used to analyze and compare the differences in age and preoperative CSF leukocyte, chloride, glucose, aspartate aminotransferase, lactate dehydrogenase, adenosine deaminase, lactic acid and protein levels between the non-infection and infection groups." (PMID 36761915, 2022). "For all patients, we analyzed age; sex; primary disease; preoperative CSF leukocyte, chloride, glucose, aspartate aminotransferase, lactate dehydrogenase, adenosine deaminase, lactic acid and protein levels; postoperative temperature; and postoperative infection." (PMID 36761915, 2022). "In addition, since higher ADA activity has been observed in monocytes/macrophages during intracellular infection by HIV due to the release of adenosine, we can presume that the ADA levels found in our patients mostly originated from these cells." (PMID 32438744, 2020). "Similar results were obtained upon infection of MF with the ADA strain." (PMID 32365752, 2020). "Traditionally, HSCT has been the treatment of choice for ADA-deficient SCID, usually performed as soon as possible following diagnosis to minimise the time exposed to high levels of toxic metabolites and before acquisition of infections." (PMID 29690908, 2018). "Without therapeutic intervention, ADA deficiency has a fatal course due to severe and overwhelming infections and most patients will die within the first year of life." (PMID 27579027, 2016). "Nevertheless, there is substantial evidence that the development of lung abnormalities in ADA deficiency is not infection related and, rather, likely to be derived from metabolic insufficiency." (PMID 27579027, 2016). "We also tested whether EHNA, another ADA inhibitor, could replace deoxycoformycin in treatment of late stage infections." (PMID 19652702, 2009). "ADA and 89.6 induced syncytia in >90% of cells by day 11 or 14 post-infection, respectively." (PMID 19088897, 2007). "However, treatment with 1 mg/ml S. fusiforme extract inhibited ADA replication (dark bars) by over 90% through day 14 after infection, which was comparable to the inhibition with ddC treatment." (PMID 16725040, 2006). "First, the parasite lacks adenosine deaminase and it is therefore less critical that the drug is protected against deamination although some protection may still be needed for the drug to be stable enough to reach the site of infection." (PMID 39607702, 2024). "Interestingly, we observed approximately 6- to 9-fold higher viral production (day 2) for MDMs cocultured with WITO-infected CD4+ T cells than for MDMs cocultured with ADA-infected cells, despite the initially comparable infection of CD4+ T cells at the time of the coculture." (PMID 34425695, 2021). "According to the literature, which is limited to case reports, the mechanism of ADA-SCID influencing aHUS development might be connected with infection, deregulation of complement function, autoimmunity, or impaired metabolism; however, no certain connections were established." (PMID 34502390, 2021). "Because complications from infections usually predominate in the clinical presentation of infants with ADA deficiency, the full spectrum of non-immunologic manifestations and their natural course may be obscured." (PMID 22969765, 2012). "Infants born with ADA-SCID have impaired immunity at birth; 3 EN patients experienced infections during the first year of treatment." (PMID 40140214, 2025). "Only six mediators, ADA, CXCL1, CCL20, MCP-3, PD-L2, and TNFSF14, differed between the “infection-free” and actively infected groups." (PMID 41387890, 2025). "False negative tests have been implicated in early infection as ADA is not active until there is lymphocytic proliferation, however the patient described in this case had symptoms of TB including prominent weight loss and pleurisy for months prior to the pleural fluid ADA testing." (PMID 34130662, 2021).
infection (continued). "One investigation reported by Nofech-Mozes studied three ADA-deficient patients who presented with neurological abnormalities (such as seizures, developmental delay, hypotonia) with no other identifiable etiology (for example, infection or transplant-related medication toxicity)." (PMID 27579027, 2016). "Introduction of both changes exerted an even greater effect on infection of CD4−CCR5+ cells, allowing a level of infection comparable to that of the ADA/Hx envelope glycoproteins with the N197S change." (PMID 21731494, 2011). "The most potent inhibitor is Rgp41A, which inhibits the infection of HeLa-CD4 cells by HIV-1 LAI and ADA Env pseudotyped viruses with IC50 values of 56 and 156 nM, respectively." (PMID 16515685, 2006). "Immunoglobulin replacement therapy (IRT), such as intravenous immunoglobulin (IVIG) is prescribed to help patients recover from active infections which is a consequence of their disease, and enzyme replacement therapy (ERT) is prescribed for ADA-SCID patients to alleviate their symptoms." (PMID 39844821, 2025). "ERT serves as an exogenous source of functional ADA enzyme, which reduces dAXP in lymphocytes and nonimmune cells, promoting immune recovery, reducing severe infections, supporting normal growth, and preventing or reversing organ damage." (PMID 40140214, 2025). "The EN group maintained optimal plasma ADA activity, increased lymphocyte counts, had manageable infections, and had no mortality for up to 30 months while on elapegademase." (PMID 40140214, 2025). "The EN group, who began elapegademase within weeks of birth without prior definitive treatment, maintained optimal plasma ADA activity, increased lymphocyte counts, had manageable infections, and had no mortality for up to 30 months while on elapegademase." (PMID 40140214, 2025). "Rates of infections were lower in patients who met both the targeted ADA and dAXP thresholds (0.85) than in those who did not meet both thresholds (1.56)." (PMID 40140214, 2025). "Adenosine Deaminase Severe Combined Immunodeficiency Disorder (ADA‐SCID), colloquially referred to as bubble‐boy disease, disrupts the immune system profoundly, leaving individuals vulnerable to life‐threatening infections." (PMID 39245805, 2024). "The non-specific inflammatory markers indicating infection, such as procalcitonin, C-reactive protein, adenosine deaminase (ADA), and lactate dehydrogenase (LDH), were significantly increased in the TM group." (PMID 36339344, 2022). "Furthermore, adenosine deaminase and chloride ion (Cl−) concentration of CSF were higher in patients in the MTB group compared with the non-infection group (p = 0.012 and 0.014, respectively)." (PMID 36180859, 2022). "Indeed, there was no detectable infection (based on intracellular Gag p24) of MDMs using WITO T/F virus (multiplicity of infection (MOI) of 5), whereas infection with a cell-free WT NL 4-3 ADA virus (M-tropic, MOI of 2) resulted in up to 5% of p24+ cells." (PMID 34425695, 2021). "Antiviral activity in supernatants was tested during ADA infection of MDM conducted in the presence or absence of BX-795." (PMID 21904615, 2011). "Antiviral activity was tested during ADA infection of MDM, conducted in the presence or absence of SB203580 and the JNK inhibitor." (PMID 21904615, 2011). "Therefore, this study demonstrates that abnormal CSF leukocyte, chloride, aspartate aminotransferase, lactate dehydrogenase, adenosine deaminase and protein levels do not increase the infection rate after ventriculoperitoneal shunt surgery." (PMID 36761915, 2022). "Preventing SARS-CoV-2 entry into lung epithelial cells and reducing the spread of infection may be possible by targeting the non-enzymatic role of ADA." (PMID 33324223, 2020). "However, administration of cordycepin did not result in a complete cure from infection, since cordycepin is rapidly converted to inactive 3′-deoxyinosine by adenosine deaminase (ADA) in vivo." (PMID 19652702, 2009).
infection (continued). "However, viruses pseudotyped with the CCR5-tropic HIV-1 ADA-Env were only able to efficiently infect differentiated THP-1-CD4R cells, although a 10-fold increase in infectious virus input was necessary to reach levels of infection comparable to VSV-G-pseudotyped HIV-1." (PMID 29301198, 2017). "While 100% productive infection and CD4+ T cell decline was seen with the ADA strain, only 50% infection and no CD4+ T cell decline was noted with the C1157 virus." (PMID 40308596, 2025). "Compared to infection without rAb-ADA, the co-administration of DENV-2 and rAb-ADA resulted in a substantial increase of inflammatory mediator genes IL-1β, IL-6, TNF-α, and CCL2 in Raw264.7 and THP-1 cells." (PMID 37794048, 2023). "Six months after infection in group 2, a high concentration of non-specific alkaline phosphatase (ALPL) and high activity of total ADA and ADA-1 were preserved." (PMID 37626725, 2023). "We reasoned that if gp120 and LukED bind to CCR5 differently, then LukEDDN would not prevent infection of CCR5-positive SupT1 cells by CCR5-tropic JR-FL- and ADA-pseudotyped HIV-1 luciferase reporter viruses." (PMID 27965453, 2016). "This registry study demonstrates that ERT-naïve infants and children with ADA-SCID (EN group) attained and maintained optimal plasma ADA activity, increased lymphocyte counts, and had manageable infection rates with no mortality while being treated with elapegademase for up to 30 months." (PMID 40140214, 2025).
metabolic disorder (14 papers, 2012 to 2025). "In humans, genes involved in the adenine rescue pathway can contribute to the development of metabolic disorders, such as mutations in adenosine deaminase (ADA) and adenine phosphoribosyl transferase (APRT)." (PMID 38829477, 2025). "On the other hand, since ADA deficiency is also classified as an inherited metabolic disorder, enzyme replacement therapy (ERT) is available as an effective therapeutic option for this disease." (PMID 37506145, 2023). "While the focus largely remains on the immunological compartment, a multi-organ pathology can be expected in a metabolic disorder, such as ADA deficiency, because of the ubiquitous nature of ADA expression." (PMID 27579027, 2016). "The liver was particularly affected – hepatocytes appeared morphologically altered, and the affected number increased with gestational age, hence indicating that the metabolic disorder underlying ADA deficiency caused pathology in the murine liver." (PMID 27579027, 2016). "We also assess the value of the ADA-deficient mouse model as a useful tool to study both immune and metabolic disease mechanisms." (PMID 22969765, 2012). "Therefore, the evidence presented so far suggests that ADA deficiency is somehow associated with the observed neurological abnormalities in this metabolic disorder." (PMID 27579027, 2016). "Recently, the Revvity NeoBase2 non-derivatized MS/MS kit introduced ADO measurement, enabling the screening of adenosine deaminase (ADA) deficiency and expanding the scope of neonatal metabolic disorder screening." (PMID 40843905, 2025). "Increased levels of ADA expression have been demonstrated to be involved in immunoinflammatory and metabolic diseases." (PMID 36267565, 2022). "Measurement of ADA levels is routine in the detection of clinical hepatic function, and recent studies have shown that it has a potential role in the assessment of metabolic diseases, inflammatory diseases, cardiovascular diseases and so on." (PMID 34319903, 2021). "ADA-SCID can be considered separately as a systemic metabolic disorder in which accumulation of toxic metabolites compromises lymphocyte and common lymphoid precursor." (PMID 24794685, 2014). "In this study, we used non-inflammatory, congenital, and metabolic diseases as references, finding that an elevated ADA level was the most common in inflammatory diseases, followed by autoimmune and malignant diseases." (PMID 35986367, 2022).
bacterial infection (12 papers, 2010 to 2025). "Another very promising therapeutic application of MΦs is direct transplantation into the lungs to treat herPAP, bacterial infections, or the lung associated phenotype of adenosine deaminase (ADA) deficiency." (PMID 32260086, 2020). "Rise in ADA-1 activity is more commonly associated with pyogenic bacterial infection of the pleural cavity, contributing to a median 70% of total ADA activity." (PMID 21811524, 2010). "According to the logistic regression model, a CSF ADA level > the normal value and the presence of external ventricular drainage/lumbar cistern drainage were associated with MDR bacterial infections." (PMID 34404351, 2021). "CSF adenosine deaminase level > the normal value and the presence of external ventricular drainage/lumbar cistern drainage were associated with MDR bacterial infections." (PMID 34404351, 2021). "In the bacterial diseases (S. suis and ETEC), pigs showed higher levels of ADA, Hp, Calp, aldolase, sAA, LDH, and TP than healthy animals." (PMID 39997755, 2025). "Similarly, the reduced expression of ADA and SIRT2, both involved in cellular senescence and inflammation, emphasizes the importance of caspase-4 in maintaining cell death and metabolic homeostasis during bacterial infections." (PMID 40137780, 2025).
genetic disorders (10 papers, 2012 to 2024). "One clinical trial dealt with the treatment of adenosine deaminase (ADA) deficiency, which is a genetic disorder leading to immunodeficiency." (PMID 23209944, 2012).
infectious disease (7 papers, 2006 to 2023). A disorder directly resulting from the presence and activity of a microbial, viral, or parasitic agent in humans. "ADA inhibitors, such as deoxycoformycin, have been shown to have anticancer effects and to be useful in the treatment of infectious diseases." (PMID 33198179, 2020). "FMD-specific missense mutations were found in two PSGs (MHC class II antigen DRA and ADA) that were classified as deleterious by PolyPhen-2, possibly contributing to immune adaptation to infectious diseases." (PMID 30903183, 2019). "So, these findings indicate that mononuclear cells contribute to the elevated serum ADA activity during infectious diseases." (PMID 27186641, 2016). "Elevated serum ADA activities have been observed in many infectious diseases mainly involving the macrophages and it has been considered as a marker of cell mediated immunity." (PMID 27186641, 2016). "Additionally, CSF ADA level can be evaluated in resource-poor settings, including small general hospitals and non-specialized hospitals for infectious diseases, and contribute to a quick and accurate diagnosis." (PMID 28028491, 2016).
neurological disorders (7 papers, 2006 to 2023). "However, previously, it was reported that increased CSF ADA level can be caused by other neurological diseases." (PMID 28028491, 2016). "It is also important to fully understand the function of ADA and the purine salvage pathway in the brain, not only to correct the abnormalities seen in ADA deficiency but also to improve therapies for other neurological disorders in which adenosine is pathologically implicated." (PMID 27579027, 2016). "However, increased CSF ADA level can be caused by other neurological diseases." (PMID 28028491, 2016). "There was a significant positive correlation (p < 0.05) between serum ADA and family history of neurological diseases in the control group." (PMID 30631381, 2018). "These speculations suggest that increased CSF ADA level can be caused by TBM and other neurological diseases." (PMID 28028491, 2016).